GSTA1 (glutathione S-transferase alpha 1)
Diseases named in the same sentence as GSTA1 in open-access papers (continued):
Sharing a sentence is not in itself a finding about the gene and the disease.
cancer (continued). "In this study, in order to gain an in-depth understanding of the roles of HPGDS, GSTZ1, and GSTA1—the less-studied members of the GST family—in tumorigenesis and development, we first performed a pan-cancer bioinformatics analysis." (PMID 36291099, 2022). "Similarly, GSTA1 contributes to chlorambucil chemoresistance, while through synergism of GSTM1 and MRP-1 cancer cells are protected from vincristine." (PMID 30487385, 2018).
tumor (23 papers, 2010 to 2025). "Combination of GSTA1 inhibitor (Curzerene) + CTNNB1 inhibitor (β-catenin-IN−2) synergistically reduces tumor growth in cells, organoids, and xenografts." (PMID 41140341, 2025). "In hepatocellular carcinoma, GSTA1 plays a tumor suppressor role via its impact on a signaling pathway involving AMP-activated protein kinase and mammalian target of rapamycin." (PMID 36291099, 2022). "GSTZ1 and GSTA1 were also significantly differentially expressed in different stages of 7 and 5 tumor types, respectively." (PMID 36291099, 2022). "IHC results indicated that GSTA1 was high in para-tumor tissues compared with that in HCC tissues (P < 0.05)." (PMID 31892975, 2020). "Analysis showed that GSTA1 abundances were lower in HCC tissues than that in adjacent para-tumor liver tissues." (PMID 31892975, 2020). "In contrast genes involved in development and differentiation (Arid5b, Inmt, Grem2, Gdap10), cell metabolism (Alas1, Gsta1, Thrsp, Fdft1, Elovl6), tumor growth (SerpinA4, Cish, Rpl36), and cell cycle control (PLK3, Myc, HNF6/Onecut1) were downregulated." (PMID 33004985, 2020). "Previous GSTA1 studies have reached contradicting conclusions, so we investigated GSTA1's effects on tumor progression and prognosis in HCC." (PMID 31892975, 2020). "Consistently with these data, GSTA1 mRNA levels were negatively correlated with tumor size (P = 0.007), and positively correlated with the mRNA expression of the liver-enriched genes albumin (P = 0.001) and procollagen type XVIII (P = 0.03)." (PMID 27936036, 2016). "Here, we showed that GSTA1 mRNA expression was down-regulated in HCCs with respect to non-tumor tissues." (PMID 27936036, 2016). "GSTA1 mRNA expression was higher in non-tumor livers than in HCCs (P = 0.007) and also higher in small than in large HCCs (P = 0.002)." (PMID 27936036, 2016). "In contrast, GSTZ1 and GSTA1 generally showed low expression in tumor tissues, which suggests that these enzymes mainly exhibit tumor suppressive effects, and that the reduction in GSTZ1 and GSTA1 levels is associated with poor prognosis of KIRC, ACC, and other tumors." (PMID 36291099, 2022). "GSTZ1 and GSTA1 are expressed at low levels in a variety of tumors and may play a role in tumor suppression." (PMID 36291099, 2022). "However, genes associated with tumor metastasis and tumor cell proliferation (SPP1, GSTA1, MAL2, and MGST1) were found to be highly expressed in LUSC1, LUSC2, LUSC4 samples." (PMID 35899203, 2022). "So, we suggested that GSTA1 may act as a biomarker in the progression of HCC, and the decrease of GSTA1 may indicate distant metastasis of the tumor and bad prognosis for HCC patients." (PMID 31892975, 2020). "Importantly, low GSTA1 expression in HCCs was proportional to high tumor size and low expression of the liver-enriched genes albumin and procollagen type XVIII." (PMID 27936036, 2016). "Actually, GSTA1 gene expression decreases in HCCs with respect to non-tumor livers." (PMID 27936036, 2016). "Furthermore, decreased GSTA1 mRNA expression in 247 HCC patients was associated with an increased risk of tumor recurrence and bad overall outcome after tumor resection." (PMID 27936036, 2016). "In addition, expression of GSTA1 mRNA was assessed by real-time PCR in 18 matching pairs of HCCs and non-tumor livers." (PMID 27936036, 2016). "Only GSTA1 low or intermediate genoytpe was associated with a non-significant protective effect for both tumour types, whereas the remaining GST classes showed contradictory effect sizes for EAC and ESCC." (PMID 23731957, 2013). "Also, we found that GSTA1 mRNA expression was lower in HCCs than in non-tumor livers." (PMID 27936036, 2016). "Dual inhibition with curzerene (a GSTA1 inhibitor) and β-catenin-IN-2 (a CTNNB1 inhibitor) synergistically reinstates ferroptotic sensitivity, suppressing tumor growth in cell lines, patient-derived organoids, and xenograft models." (PMID 41140341, 2025).
tumor (continued). "In contrast, garlic oil upregulates HO-1, glutathione S-transferase alpha 1 (GSTA1), and NQO1 and significantly reduces tumor formation in tobacco compound 4-(methylnitrosamino)-1-(3-pyridyl)-1-butanone-exposed mice." (PMID 40722961, 2025). "Unfortunately, the GSTA1 protein was undetectable in GBM and normal brain samples according to UALCAN, but the GSTA1 protein levels were found to be decreased in several tumor types, with only OV showing increased GSTA1 levels." (PMID 36291099, 2022). "Alongside, Gsta1 and Atf3 were upregulated in HCC mice, which have been proposed as potential tumor suppressors in HCC development." (PMID 32559205, 2020). "The aim of this study is to investigate the effect of Glutathione S-transferase A1 (GSTA1) on the prognosis of HCC and to understand its role in tumor progression and the possible mechanism." (PMID 31892975, 2020). "Higher GSTA1 was correlated with longer OS and DFS in single tumor number and TNM stage I+II (all P < 0.05)." (PMID 31892975, 2020). "Multivariate analysis was performed using the Cox Proportional hazards model and the analysis revealed that GSTA1, AFP, tumor number, PVTT and TNM were independent prognostic factors for HCC (all P < 0.05)." (PMID 31892975, 2020). "In this study, we aimed to clarify GSTA1's effect on HCC prognosis and to determine its role in tumor progression." (PMID 31892975, 2020). "Univariate analysis showed that GSTA1, AFP, tumor number, tumor size, PVTT, and TNM stage were related to OS and DFS in HCC patients." (PMID 31892975, 2020). "Therefore, it is reasonable to ask whether GSTA1 functions as a tumor suppressor." (PMID 27936036, 2016). "P1, which constituted a major fraction of HB tumor cells and had the highest C1 group score, exhibited a more mature hepatocyte-like phenotype, expressing the highest level of ALB as well as liver metabolism genes (e.g., CYP2E1, GSTA1, G6PC)." (PMID 35860547, 2022). "Indeed, other polyphenolic compounds, such as luteolin and quercetin, have been reported to activate the expressions of glutathione S-transferases, Gsta1 and Gstt2, and decrease the levels of reduced glutathione in LC540 tumor Leydig cells." (PMID 35723385, 2021). "Surprisingly, Epi_HSPA1A, Epi_GSTA1, Epi_SPP1 showed two distinctive CNV states between normal and tumor tissue, according to which we divided these cells into two clusters, ductal-normal cells from normal tissues and ductal-tumor cells from tumor tissues." (PMID 35087839, 2021). "Because the SNP rs3957357C>T is known to reduce GSTA1 transcriptional activity, we analyzed GSTA1 mRNA expression by real-time PCR in 18 matching pairs of tumor and non-tumor liver tissues from patients undergoing resection of HCCs." (PMID 27936036, 2016). "In addition, GSTA1, GSTM1, and GSTZ1 are reported to be downregulated in tumor tissue and can correlate with a poor prognosis, while GSTT1, GSTO1, and GSTK1 are mostly reported to be upregulated in tumor tissue compared to the normal surrounding tissue." (PMID 33228209, 2020). "Their trend of expression showed most of them to be upregulated in the tumor samples, regardless of the disease stage, while only PPL, ALDH1A1, GSTA1, TJP3 and CRYAB were downregulated in HNSCC." (PMID 37686696, 2023). "However, GSTA1 was not related to HCC patients' age, gender, HBsAg, tumor number or tumor size." (PMID 31892975, 2020).
cardiovascular disease (2 papers, 2023 to 2024). "In the case of cardiovascular diseases, the differences in the influence of GSTM1, GSTT1, GSTP1 and GSTA1 polymorphisms on their development or lack of it depending on the continent were shown." (PMID 37819495, 2023).
prostate (2 papers, 2016 to 2025). "The high expression of GSTA1 in PIA suggests that the affected cells are experiencing increased oxidative stress, while the low expression of GSTA1 in adenocarcinoma indicates a deficiency in detoxifying ROS, implicating increased oxidative stress in the transition from prostatitis to PCa." (PMID 40178629, 2025). "Low levels of GSTA1 and GSTP1 are suggested to contribute to prostate carcinogenesis." (PMID 28035996, 2016).
adenocarcinoma (1 paper, 2025). A common cancer characterized by the presence of malignant glandular cells. "Conversely, Parsons found that normal peripheral zone epithelial cells rarely express GSTA1, whereas GSTA1 expression is significantly elevated in PIA but reduced in adenocarcinoma." (PMID 40178629, 2025).
colon (1 paper, 2020). "Our results indicate a suppression of enzymes involved in various stages of carcinogen breakdown including CYP2C8, CYP4F12, GSTA1, and UGT1A within right colon tumors." (PMID 32293332, 2020).
kidney disease (1 paper, 2023). "Only urine GSTA1 was common among both AKI and CKD/ESKD patients for differentiating kidney disease from healthy control subjects." (PMID 38040779, 2023).
metabolic disease (1 paper, 2024). A congenital disorder (due to inherited enzyme abnormality) or acquired (due to failure of a metabolically important organ) disorder resulting from an abnormal metabolic process. "Also, the increase of GSTA1 by bicyclol treatment resulted in a decrease in FABP1 levels and an improvement of the disease, highlighting a possible mechanism of action of GSTA1 in metabolic diseases." (PMID 38791126, 2024).
GSTA1 also shares sentences with these, for which no sentence is quoted: infection (3 papers); Sinusoidal Obstruction Syndrome (2); acute leukemia (1); Arthritis (1); asthma (1); Balkan Endemic Nephropathy (1); basal cell carcinoma (1); cervical cancer (1); ciliopathies (1); colorectal adenocarcinoma (1); end-stage renal disease (1); fungal infection (1); glomerulosclerosis (1); Hepatic Injury (1); Hypertension (1); injury (1); kidney cancer (1); kidney injury (1); metabolic dysfunction-associated steatotic liver disease (1); myopathies (1); nephritis (1); neutropenia (1); osteoporosis (1); ovarian carcinoma (1); Pneumocystis infection (1); progressive myoclonus epilepsy (1); proliferative inflammatory atrophy (1); Renal cyst (1); squamous cell carcinoma (1); Strabismus (1).